IGKV4-1 (immunoglobulin kappa variable 4-1)
Description:
V segment of the variable domain of immunoglobulins light chain that participates in the antigen recognition. Immunoglobulins, also known as antibodies, are membrane-bound or secreted glycoproteins produced by B lymphocytes. In the recognition phase of humoral immunity, the membrane-bound immunoglobulins serve as receptors which, upon binding of a specific antigen, trigger the clonal expansion and differentiation of B lymphocytes into immunoglobulins-secreting plasma cells. Secreted immunoglobulins mediate the effector phase of humoral immunity, which results in the elimination of bound antigens. The antigen binding site is formed by the variable domain of one heavy chain, together with that of its associated light chain. Thus, each immunoglobulin has two antigen binding sites with remarkable affinity for a particular antigen. The variable domains are assembled by a process called V-(D)-J rearrangement and can then be subjected to somatic hypermutations which, after exposure to antigen and selection, allow affinity maturation for a particular antigen.
Synonyms: IGKV41; B3
Tractability: Antibody: its Gene Ontology location is reachable by antibodies, with high confidence; UniProt places it where antibodies can reach, with medium confidence; UniProt predicts a signal peptide or a membrane-spanning region.
Gene: Immunoglobulin variable (V) gene on chromosome 2 (88,885,397 to 88,886,153, forward strand). Ensembl gene ENSG00000211598.
Subcellular location: Secreted; Cell membrane
Pathways (Reactome):
Immune System: Antigen activates B Cell Receptor (BCR) leading to generation of second messengers; CD22 mediated BCR regulation; Classical antibody-mediated complement activation; FCERI mediated Ca+2 mobilization; FCERI mediated MAPK activation; FCERI mediated NF-kB activation; FCGR activation; Fc epsilon receptor (FCERI) signaling; Immunoregulatory interactions between a Lymphoid and a non-Lymphoid cell; Initial triggering of complement; Regulation of Complement cascade; Regulation of actin dynamics for phagocytic cup formation; Role of LAT2/NTAL/LAB on calcium mobilization; Role of phospholipids in phagocytosis
Disease: FCGR3A-mediated IL10 synthesis; FCGR3A-mediated phagocytosis; Potential therapeutics for SARS
Hemostasis: Cell surface interactions at the vascular wall
Vesicle-mediated transport: Scavenging of heme from plasma
Gene Ontology:
Molecular function: antigen binding
Biological process: immune response
Cellular component: blood microparticle; extracellular region; immunoglobulin complex; plasma membrane
Homologues: Orthologues: macaque IGKV4-1 (94% identical), mouse Igkv8-27 (81% identical), mouse Igkv8-30 (80% identical), mouse Igkv8-28 (79% identical), mouse Igkv8-19 (78% identical), mouse Igkv8-24 (77% identical), mouse Igkv8-21 (76% identical), dog IGKV4-1 (72% identical), mouse Igkv8-34 (71% identical), mouse Igkv8-18 (69% identical), mouse Igkv8-26 (69% identical), mouse Igkv8-16 (65% identical), and 2 more. Paralogues in human: IGKV1-27 (64% identical), IGKV1-39 (64% identical), IGKV1D-39 (64% identical), IGKV3-15 (64% identical), IGKV3D-7 (64% identical), IGKV3OR2-268 (64% identical), IGKV3-20 (63% identical), IGKV1-33 (62% identical), IGKV1-8 (62% identical), IGKV1D-33 (62% identical), IGKV3D-15 (62% identical), IGKV3D-20 (62% identical), and 81 more.
Diseases named in the same sentence as IGKV4-1 in open-access papers:
IGKV4-1 is named in the same sentence as 11 diseases in open-access papers, as found by Europe PMC text mining. Sharing a sentence is not in itself a finding about the gene and the disease. The quoted sentences say what the papers report.
lung carcinoma (3 papers, 2020 to 2023). "The remaining six genes (IGKV4‐1, IGKV6D‐41, TNFRSF11A, INHA, IL11 and SCH3) have not been reported in the literature and may be used as potential biomarkers for lung cancer research." (PMID 32686362, 2020).
COVID-19 (2 papers, 2023 to 2024). A disease caused by infection with severe acute respiratory syndrome coronavirus 2. "The levels of immunity-related proteins (IGHG1, IGLL5, and IGKV4-1) were slightly decreased in the acute phase of COVID-19, confirming that immunity had been suppressed." (PMID 38965561, 2024). "Specifically, signatures of plasma cells (IGHG3, IGKC, IGHM, JCHAIN, IGHG2, IGKV4-1, IGLV3-1, IGHA1), activated fibroblasts (COL1A1, COL1A2, COL3A1), inflammatory cytokines (CXCL9, CCL18) and complement factors (C1QB, C1QC) dominated the DE genes for the COVID-19 lung sections." (PMID 37858234, 2023).
celiac disease (1 paper, 2016). An autoimmune genetic disorder with an unknown pattern of inheritance that primarily affects the digestive tract. "Indeed, IGKV4-1 has previously been shown to be overrepresented in systemic lupus erythromatosus, celiac disease, and type 1 diabetes, and we have also shown that its actual expression in the peripheral repertoire is significantly lower than its frequency of rearrangement in the genomic DNA." (PMID 27994589, 2016).
hepatitis B virus (1 paper, 2019). "Six IA genes, APOB, IMPDH1, SEC61G, IQGAP2, TAGAP, and IGKV4-1, were dysregulated (differential expression, p < 0.05) in only tumor samples of drinkers without hepatitis B virus (HBV) infection as compared to pure normal samples (from nondrinkers)." (PMID 31480259, 2019).
mantle cell lymphoma (1 paper, 2022). Mantle cell lymphoma is a rare form of malignant non-Hodgkin lymphoma affecting B lymphocytes in the lymph nodes in a region called the ``mantle zone''. "IGKV4-1 is involved in the protection of acute rejection and considered an effective biomarker for the early identification of mantle cell lymphoma." (PMID 35745003, 2022).
tumor (3 papers, 2019 to 2023). "In the current SCLC cohort, downregulation of the inflammation marker (IGKV4-1), the tumor aggressivity associated marker (QSOX1), and the tumor suppressor marker (TGFβ1) were observed." (PMID 34996345, 2022). "In addition, the lesion IgG + and mucosa IgA + spots exhibited divergent B-cell receptor V/C gene usage, with IGLC2, IGLC3, IGLV3-1, and IGKV4-1 all enriched in the tumor, suggesting a difference in the adaptive response between the two plasma cell types." (PMID 38110959, 2023).
IGKV4-1 also shares sentences with these, for which no sentence is quoted: bladder cancer (1 paper); infection (1); liver fibrosis (1); metastatic tumors (1); type 1 diabetes (1).